CD4 (CD4 molecule)
Diseases named in the same sentence as CD4 in open-access papers (continued):
Sharing a sentence is not in itself a finding about the gene and the disease.
rheumatoid arthritis (continued). "An accumulation of cytotoxic CD4+ T cells was observed in patients with multiple sclerosis (MS), inflammatory bowel disease (IBD), rheumatoid arthritis (RA), and ankylosing spondylitis." (PMID 32226027, 2020). "The frequencies of various subsets of CD4+ T cells, B cells, monocytes and NK cells in PBMC were assessed in 30 healthy controls (HC), 30 rheumatoid arthritis (RA) patients and 26 SLE patients using flow cytometry." (PMID 31354747, 2019). "CD4+CD28− T cells exhibit autoreactive potential in autoimmune disorders, including rheumatoid arthritis (RA)." (PMID 28320444, 2017). "The CD4+CD28- lymphocytes are suggested to acquire their phenotype in relation to increased proinflammatory state of the individual (notably increased levels of TNF), and themselves participate in inflammatory processes including rheumatoid arthritis, chronic kidney disease and atherogenesis." (PMID 23835405, 2013). "Interestingly, our analysis of the gene expression profile of NKG2D+ CD4+ T-cells revealed an increased expression of the two receptors, CX3CR1 and CKMLR1, both of which have been suggested to be involved in the pathology of rheumatoid arthritis." (PMID 22870231, 2012). "CD4+ T lymphocyte mediates many self-antigen reactive or inflammatory diseases, such as multiple sclerosis (MS), inflammatory bowel disease (IBD), rheumatoid arthritis (RA), and so on." (PMID 40235598, 2025). "Using high‐dimensional mass cytometry and functional profiling, we show that cytomegalovirus (CMV) drives expansion of cytotoxic CD27−CD28− CD4+ T cells, whereas rheumatoid arthritis (RA) exerts nonredundant effects by modulating their effector capacity." (PMID 41235706, 2025). "Increased Arid5a levels in the CD4+ T-cells of untreated rheumatoid arthritis (RA) patients are reduced by the anti-IL-6 receptor antibody tocilizumab, implicating the contribution of the IL-6-ARID5A axis in RA pathogenesis." (PMID 39682280, 2024). "These CD4+CD25lowFoxp3low Tregs are termed "ex-Tregs" or "exFoxp3" cells, which have been identified in mouse models of diabetes, multiple sclerosis (EAE) and rheumatoid arthritis (RA)." (PMID 38566233, 2024). "In rheumatoid arthritis (RA), IL17 in synovial fluid may be involved in the downregulation of EZH2 in CD4+ T cells, implying that enhanced TH17 differentiation may impair the function of the CD30+ Treg subset." (PMID 39170389, 2024). "To characterize the remaining 60% of GWAS loci without colocalization, we collected H3K27ac profiles of 5 immune cell types (CD4+ T cells, CD8+ T cells, regulatory T cells, monocytes, and B cells) from rheumatoid arthritis (RA) patients and healthy controls using CUT&Tag." (PMID 33926512, 2021). "However, the involvement of CD4+ T cells and its relationship with TNFR1 have been demonstrated in other chronic inflammatory diseases such as rheumatoid arthritis (RA)." (PMID 30847024, 2019). "Previous studies have shown that the inhibition of CD4+CD25+Foxp3+Tregs result in the functional impairment or decrease in the number of cells in various ADs such as multiple sclerosis (MS) and rheumatoid arthritis (RA)." (PMID 29191190, 2017). "Previous studies indicated an abnormal phenotype and impaired function of synovial Tregs in rheumatoid arthritis (RA) and increased FOXP3 expression in synovial CD4+ T cells in rheumatoid factor (RF)-negative RA and PsA compared to seropositive RA." (PMID 28679449, 2017). "The humanized non-depleting anti-CD4 monoclonal antibody Tregalizumab (BT-061) is able to selectively activate the suppressive function of regulatory T cells and has been investigated up to phase IIb in clinical trials in patients suffering from rheumatoid arthritis (RA)." (PMID 28090323, 2016). "Nearly 20 years ago, a unique CD4+ T cell type lacking the expression of costimulatory CD28 surface receptors was first described in rheumatoid arthritis (RA) patients." (PMID 25834833, 2015).
rheumatoid arthritis (continued). "Indeed, NKG2D+ CD4+ T cells, not present in healthy individuals, have been reported to be involved in the patho-physiology of several immune-mediated diseases such as rheumatoid arthritis, Crohn’s disease, Wegener’s granulomatosis, and human cytomegalovirus (HCMV) infection." (PMID 23056001, 2012). "The purpose of this study was to evaluate the safety, tolerability, pharmacokinetics (PK) and pharmacodynamics (PD) of the humanized anti-CD4 monoclonal antibody MTRX1011A in a randomized, double-blind placebo-controlled Phase 1 study in patients with rheumatoid arthritis (RA)." (PMID 22029963, 2011). "This CD4− cluster largely expressed Foxp3, Helios, and TIGIT as well as CD25, CD39, CTLA-4, CD71, HLA-DR, and low CD127, thus mirroring CD8+ Treg-like cells which have been described in inflamed joints of rheumatoid arthritis (RA), psoriatic arthritis (PsA), and spondylarthritis." (PMID 39101538, 2024). "In rheumatoid arthritis, circulating pathogenic CD4+ T cells with the same gene signature as their tissue were also described, suggesting that they represent “ex-TRM cells” At present, it is not known yet whether circulating “ex-CD4+ TRM“ cells are present in patients with active IBD." (PMID 34440651, 2021). "CD4+ helper T cells (Th) 1 are key regulators in the tumor immune microenvironment and have a crucial role in activating cytotoxic T lymphocytes, participating in the pathological response process of inflammatory bowel disease (IBD) and rheumatoid arthritis (RA)." (PMID 33123120, 2020). "In rheumatoid arthritis, the substantial amount of soluble MIC released by synoviocytes failed to downregulate NKG2D on CD4+ T cells, possibly due to high levels of IL-15 and TNF-α." (PMID 30150983, 2018). "In patients with rheumatoid arthritis, soluble MICA failed to downregulate NKG2D on CD4+ T cells and CD8+ T cells, possibly due to counteractions of IL-15 and TNF-α." (PMID 30150983, 2018). "Additionally, the ‘ARLA motif’ was almost absent in the SF CD4+ T cell repertoire in patients with JIA and rheumatoid arthritis (RA)." (PMID 38963700, 2024). "The mutual correlation among soluble CD4 (sCD4), soluble CD8 (sCD8), and soluble CD23 (sCD23) has not yet been studied in patients with rheumatoid arthritis (RA), although previous studies have demonstrated that certain soluble markers of immune activation are elevated in RA." (PMID 18475737, 1996).
malaria (552 papers, 2004 to 2026). Malaria is a serious and sometimes fatal disease caused by a parasite that commonly infects a certain type of mosquito which feeds on humans. "HIV infection can impair antimalarial immunity, and CD4+ T cell depletion is a major factor in determining malaria susceptibility." (PMID 40950582, 2025). "HIV has been associated with severe malaria presentation in untreated HIV patients with low CD4 count." (PMID 40847278, 2025). "Particularly, high accessibility was observed in CD4+ T at the malaria-associated regulatory region and the LAX1 promoter." (PMID 40441141, 2025). "Clinical studies have demonstrated that low CD4+ T cell counts are strongly associated with increased malaria susceptibility and more severe clinical outcomes in HIV-infected individuals." (PMID 40950582, 2025). "HIV also worsens the effects of malaria, enhances malaria communicability, and causes strong CD4 cell activation and expression of cytokines." (PMID 40896267, 2025). "Children <5 years, those between 5 and 9 years, children not on ART and Cotrimoxazole, febrile children, children with viral load >1000 copies/μL, and CD4 count <2000 cells/ μL were factors associated with malaria parasitemia among HIV-infected children." (PMID 39559371, 2024). "There is considerable evidence that HIV and malaria co-infections act synergistically; individuals with HIV are more susceptible to symptomatic malaria, and those with malaria experience higher viral loads and lower CD4+ counts." (PMID 39460363, 2024). "In a study conducted in a malaria-endemic area, mothers co-infected with HIV and malaria and having severe immunodeficiency (CD4 cell count < 200 cells/mm3) are at increased risk for placental malaria and the babies are at increased risk of congenital malaria." (PMID 38840266, 2024). "Activated dendritic cells are highly associated with polyfunctional CD4+ T cell responses to malaria." (PMID 39041038, 2024). "To explore the functional role of RACK1 in CD4+ T cell-mediated immunity to blood-stage malaria, we employed a murine model caused by P. yoelii 17XNL, in which CD4+ T cell-dependent immunity is responsible for full resolution of the infection." (PMID 39024388, 2024). "Clusters of CD4+ and γδ T cells associated with protection were identified, consistent with their known role in malaria immunity." (PMID 38716733, 2024). "CD4 T cells are required, along with antibodies, for complete protection from blood-stage infection with Plasmodium spp., which cause malaria." (PMID 36920200, 2023). "The published risk factors associated with HIV and malaria, namely CD4+ level, ART consumption, sex, education, gravidity and age, were analyzed." (PMID 36104731, 2022). "It is assumed that the increased susceptibility of HIV-seropositive individuals to malaria is related to some immune system-modulating mechanisms, such as depletion of CD4+ cells." (PMID 36104731, 2022). "We found that a pre-existing malaria caused animals to produce a greater number of CD4+CCR5+ T cells for SIV replication, resulting in higher viral loads." (PMID 35778766, 2022). "Results from a community cohort in Kenya demonstrated similar findings: adults with advanced HIV-1 (lower CD4+ T-cell counts) and malaria had higher parasitemias and were at increased risk for clinical malaria." (PMID 36506016, 2022). "Based on these findings, severe malaria was significantly associated with declined CD4+ and CD8+ T cell counts, upregulation of IL-6, and high serum levels of oxidative stress biomarkers." (PMID 35223394, 2021). "Some studies have shown that the risk of malaria severity increases in HIV patients with a CD4 + T cell count < 200 × 106 cells/L or < 350 cells/μL." (PMID 33407474, 2021). "Inflammatory CD4+ T-cells that produce IFNγ and TNFα have been implicated in conferring protection from malaria in adults by preventing P. falciparum infection or its replication such that higher parasitemia and clinical malaria are diminished." (PMID 34414129, 2021).
malaria (continued). "Essentially, severe malaria has repeatedly been reported to cause decline in CD4+ T cell counts and induction of anemia through CD8+ T cell-dependent plasmodial clearance which invariably leads to rise in oxidative stress." (PMID 35223394, 2021). "Most relevant to our work is the finding that differential CD4 T cell response profiles were seen with sequence variants of TH2R/R2 region of PfCSP (synthesized as peptides) when assessed ex vivo with PBMCs from malaria-exposed individuals." (PMID 34168657, 2021). "Therapeutically, LD01 treatment of mice infected with a lethal malaria strain resulted in survival that was associated with lower numbers of FOXP3+Tbet+CD4+ regulatory T cells." (PMID 32733457, 2020). "By studying immune responses after single CHMIs and CPS immunization regimens we found that volunteers are generally predisposed, by the inhibitory ligand expression of their CD4+ T cells, to respond to their first malaria encounter in a fast or slow fashion." (PMID 31605396, 2020). "CD4+ T cell functional inhibition (exhaustion) is a hallmark of malaria and correlates with impaired parasite control and infection chronicity." (PMID 32817333, 2020). "Cellular immunity to malaria is typically thought to involve IFN-γ produced by Th1 CD4+ T cells; however, both type I and II interferons have been implicated in the immune response to malaria." (PMID 30862316, 2019). "The association of inhibitory markers on CD4+ T cells and parasitaemia for the symptomatic malaria population." (PMID 31316497, 2019). "Low CD4 counts were associated with high density malaria parasitaemia and consequently, very high CD4 counts seemed to exhibit low malaria parasite density among PLWHA." (PMID 31354844, 2019). "Our results identify specific clusters of CTLA-4+PD-1+CD4+ T cells which are associated with malaria complications." (PMID 29555909, 2018). "Our study aimed to identify CD4+ T cell signatures that were associated with protection from severe and/or clinical malaria." (PMID 29555909, 2018). "Both γδ T cells and CD4+ T cells have been implicated in immunity to malaria, but their association with natural gain or loss of infection has not been studied before." (PMID 28821806, 2017). "To investigate the role of CD4 T cells in immunity to malaria, we measured associations of Pf-specific CD4 cytokine-producing cells with the prospective risk of Pf infection and clinical malaria, adjusting for household exposure to Pf-infected mosquitos." (PMID 29097996, 2017). "Malaria infection was significantly associated with thrombocytopenia, whereas malaria parasitic density and CD4 + count were significantly associated with leucopenia." (PMID 28184306, 2017). "A significant association was observed between prevalence of malaria and CD4+ T cell count (p < 0.001)." (PMID 27619013, 2016). "Due to the importance of the IFN-γ in immunity against malaria, it would be anticipated that delayed acquisition of P. falciparum antigen-specific IFN-γ-producing CD4+ T cells would lead to increase risk to asymptomatic and clinical malaria." (PMID 27165269, 2016). "The finding of a significant association between malaria prevalence and CD4+ T cell count is contrary to studies performed elsewhere." (PMID 27619013, 2016). "This study was designed to determine the prevalence of malaria in PLWHIV in Yaounde, Cameroon, as well determine the association between CD4+ T cell count and malaria in the study population." (PMID 27619013, 2016). "In a study in rural Uganda, HIV infected ART-naïve adults with CD4 counts <200 cells/μl had a significantly higher risk of clinical malaria than those with CD4 counts ≥500." (PMID 27417903, 2016). "During blood stage infection, acute pro-inflammatory cytokine-mediated effector responses from CD4+ T cells can restrict growth of the malaria parasites and reduce risk of clinical disease." (PMID 27165269, 2016).
malaria (continued). "This CD4+ T cell population was specifically expanded in experimental blood-stage malaria infection and was significantly associated with reduced parasite burden." (PMID 27662621, 2016). "In the present study, data demonstrated that patients with P. vivax recurrent malaria presented an unbalanced CD4+/CD8+ T-cell ratio, which was associated with a significant increase in the plasmatic IL-10 levels." (PMID 27581163, 2016). "During malaria, CD4+ T− helper cells have been implicated for pathogenesis, protection and immune evasion of parasites." (PMID 27799922, 2016). "A recent report associated CD4+ T cells expressing the degranulation marker CD107a with protection against malaria in sporozoite-immunized volunteers, and CD38 has been implicated in the cytotoxic activity of NK cells." (PMID 27662621, 2016). "One possible explanation for these findings is that there is a threshold below which CD4 count significantly influences the risk of malaria." (PMID 27417903, 2016). "This study was therefore designed to determine the prevalence of malaria in people living with HIV (PLWHIV) in Yaounde, Cameroon, and also to determine the association between the CD4+ T cell count and malaria." (PMID 27619013, 2016). "HIV-1 infected adults have a higher risk of malaria infection and clinical malaria, the latter increasing with falling CD4-cell count." (PMID 25592254, 2015). "In a placebo-controlled randomized controlled trial in Malawi, researchers showed that iron supplementation in anemic HIV-infected children had beneficial effects on hemoglobin, anemia prevalence and CD4 counts at 6 months but increased the risk of malaria." (PMID 26482352, 2015). "In Kenyan adults with natural immunity to malaria, CD4+CD25HI T-cell frequency at enrollment was associated with the risk of developing clinical malaria during follow-up." (PMID 26029205, 2015). "Confirmed or suspected malaria-related fever was associated with lower CD4 cell count at inclusion, having started antiretroviral therapy before the inclusion and having experienced symptomatic malaria at the beginning of the pregnancy." (PMID 24996807, 2014). "This work confirms the role of CD4 immunodepression as a major determinant for the risk of malaria-related fever in HIV-infected pregnant women, already established in HIV-infected adults." (PMID 24996807, 2014). "Of interest, we observed that DBLα-tag–specific CD4+IL-4+ T cells were associated with delayed time to subsequent malaria episode over a period of 1 y, suggesting a possible role for IL-4–secreting CD4+ T cells in protection." (PMID 24453249, 2014). "We further observed that heavy malaria exposure was associated with a decreased ability of CD4+ T cells to proliferate in response to malaria antigens, and that this impaired proliferation is partially reversed by IL-10 blockade." (PMID 24415936, 2014). "In humans, several studies reported an association of IFN-γ production by CD4+ T cells but also NK and γδ T cells with protection from symptomatic malaria (reviewed in Ref." (PMID 24453249, 2014). "TNF-alpha producing CD4 T cells were independently associated with decreased risk of malaria (OR = 0.63, p value = 0.027) while malaria exposure was associated with increased risk for clinical malaria (OR = 11.24, p value = 0.005)." (PMID 25506706, 2014). "In the final models, confirmed malaria-related fever was associated to CD4 cell count at inclusion and having experienced symptomatic malaria at the beginning of the pregnancy." (PMID 24996807, 2014). "A CD4 count ≤350 cells/mm3 was associated with a higher risk of helminth infections (odds ratio, 3.39; 95% CIs, 2.16–5.33; p<0.0005) and malaria (3.37 [2.11–5.38]; p<0.0005) whilst helminth infection was a risk factor for malaria infection and vice versa." (PMID 23967365, 2013).